HMGB1 (high mobility group box 1)
Diseases named in the same sentence as HMGB1 in open-access papers (continued):
Sharing a sentence is not in itself a finding about the gene and the disease.
coronary artery disease (continued). "The levels of HMGB1 were positively correlated with hs-CRP and cardiac troponin I levels (r=0.657 and 0.554, respectively; both P<0.01) in patients with coronary artery disease." (PMID 23935732, 2013). "The levels of HMGB1 were positively correlated with those of hs-CRP (r=0.657, P<0.01) and cTnI (r=0.554, P<0.01) in patients with coronary artery disease." (PMID 23935732, 2013). "The levels of serum HMGB1, hs-CRP and cardiac troponin I were measured in 98 patients with coronary artery disease and in 30 healthy subjects." (PMID 23935732, 2013). "Studies evaluating atherosclerotic disease progression in non-diabetic patients with coronary artery disease and diabetic patients with coronary artery stenosis or peripheral artery disease reported markedly elevated serum HMGB-1 levels." (PMID 37513606, 2023). "It has been also shown that HMGB1 is involved in non-calcified coronary plaques and remodeled plaques in patients with stable coronary artery disease." (PMID 34044825, 2021). "In patients with and without T2DM, elevated serum HMGB-1 levels are related to coronary heart disease and are closely related to the severity of coronary artery stenosis." (PMID 34631895, 2021). "As both HMGB1 and TMAO are shown to be involved in inflammation as well as coronary artery disease, we tested whether TMAO upregulates the expression of HMGB1 in endothelial cells." (PMID 31336567, 2019). "Apart from detection of HMGB1 in atherosclerotic plaques, HMGB1 levels were shown to be significantly upregulated in coronary artery disease in both diabetic as well as non-diabetic patients." (PMID 31336567, 2019).
Hepatitis (21 papers, 2011 to 2025). Inflammation of the liver. "The role of HMGB1 in the precise mechanism of apoptotic cell death of hepatocytes in this experimental hepatitis remains to be unknown but is assumed to be implicated in the signal pathways regulating apoptosis." (PMID 24690901, 2014). "Together, H. hepaticus infection promotes hepatitis to develop hepatic preneoplasia by activation and accumulation of HMGB1." (PMID 35046917, 2021). "Moreover, cynaroside decreased the expression of IL-1β, IL-6 and TNF-α,and inhibited HMGB1 in cecal ligation and puncture-induced liver inflammation." (PMID 38835771, 2024). "In addition, the HMGB1-TLR signaling pathway was involved in the protective role of Ketanserin in Con A-induced hepatitis." (PMID 31998441, 2020). "Therefore, HMGB1 is an important target for the alternation from hepatitis to tumor or early hepatocarcinogenesis." (PMID 26393575, 2015). "Serum HMGB1 levels (ng/ml) in patients with hepatitis and normal controls." (PMID 25356587, 2014). "Furthermore, we aimed to evaluate the effect of GL as an inhibitor of HMGB1 upon the expanded kinetics of experimental hepatitis in mice treated with LPS/GaIN." (PMID 24690901, 2014). "Based on these results, we conclude that ethyl pyruvate pretreatment may ameliorate ConA-induced hepatitis partly through downregulation of HMGB1." (PMID 24498418, 2014). "It has been reported by Gong that HMGB1 can exacerbate Con A-induced hepatitis." (PMID 24498418, 2014). "This indicates that HMGB1 may serve a pivotal role in the later processes of Con A-induced hepatitis." (PMID 24498418, 2014). "HMGB1 is likely to be crucial in initiating and mediating hepatitis." (PMID 25356587, 2014). "Quercetin was shown to reduce the expression of high mobility group box 1 (HMGB1) and the mRNA and protein levels of TLR2 and TLR4 in liver tissues of mice with hepatitis." (PMID 31714944, 2019). "Therefore, we asked whether ethyl pyruvate acts by inhibiting HMGB1 in ConA-induced hepatitis." (PMID 24498418, 2014). "But, the interaction of HMGB1/RAGE with IL-17 has been not investigated in liver inflammation with HB." (PMID 26391982, 2015). "An interesting recent study reported that inhibition of HMGB1/TLR4 intracellular signaling decreased production of NF-κB, TNF-α, and IL-6 in cholestatic liver inflammation, which further confirms the close interactions among HMGB1, TLR4, and NF-κB in the promotion of liver inflammation." (PMID 35335612, 2022). "Indeed, similar to HMGB1, the high level of RAGE was required for hepatitis as well as HCC." (PMID 26393575, 2015). "Concurrently, we found that the average level of HMGB1 expression in the blood of obese combined HBV-infected HCC patients was higher than that of others, and the expression of HMGB1 was not high in normal weight and non-hepatitis patients." (PMID 34583662, 2021).
lymph node metastasis (21 papers, 2009 to 2025). "On the whole, the results indicated that HMGB1 was overexpressed in the majority of patients and was associated with lymph node metastasis and a poor prognosis." (PMID 35280439, 2022). "Higher related to lymph node metastasis risk, later clinical stage and tumor size, suggesting a potential contributory role of HMGB1 in tumorigenesis of thyroid cancer." (PMID 31331356, 2019). "Blood loss (≥ 800 ml), intraoperative transfusion, advanced T stage (T2, T3a), lymph-node metastasis, and HMGB1 high expression were significantly associated with shorter overall survival." (PMID 31399104, 2019). "In the mentioned study, serum HMGB1 levels were demonstrated to be significantly associated with the depth of invasion, lymph node metastasis, tumor size, and poor prognosis." (PMID 30245980, 2018). "HMGB1 overexpression was significantly associated with tumor invasion, lymph node metastasis, distant metastasis and Duke's stage, and inversely associated with overall survival." (PMID 20579387, 2010). "Serum HMGB1 levels were significantly associated with depth of invasion, lymph node metastasis, tumor size, and poor prognosis (p < 0.05)." (PMID 19476625, 2009). "This study found that serum levels of HMGB1 were associated with depth of invasion (T stage), lymph node metastasis (N stage), tumor size, and poor prognosis." (PMID 19476625, 2009). "In addition, HMGB1 protein overexpression has been shown to be involved in lymph node metastasis and to be associated with a poor prognosis of patients with LSCC, as we have found." (PMID 35280439, 2022). "Furthermore, lymph node metastasis and stage progression were associated with a high plasma HMGB1 concentration, which was identified as an independent predictive factor for RFS." (PMID 35328684, 2022). "The HMGB1 overexpression and higher M2 macrophage density were involved in lymph node metastasis (P < 0.01) and poor prognosis (P < 0.05)." (PMID 35280439, 2022). "Increasing evidence has suggested that HMGB1 and M2 macrophages are involved in lymph node metastasis." (PMID 35280439, 2022). "Among the LSCC samples with lymph node metastasis, the HMGB1 expression was high in 41 samples (33.4%)." (PMID 35280439, 2022). "A high HMGB1 expression was significantly associated with an advanced stage (stages III and IV; P < 0.001) and lymph node metastasis (P < 0.001)." (PMID 35280439, 2022). "Univariate analysis revealed that pM stage, lymph node metastasis, venous invasion, HMGB1 expression, and co-expression of HMGB1 and RAGE were significantly associated with poor survival rates (P ≤ 0.05, P ≤ 0.001)." (PMID 35829833, 2022). "And HMGB1 up-regulation was rather prevalent in thyroid cancer tissues and closely correlated with worse overall lymph node metastasis and clinical stage." (PMID 31331356, 2019). "Multivariate analysis showed that transfusion, lymph-node metastasis, and high HMGB1 expression were independent predictors of poor overall survival." (PMID 31399104, 2019). "The grade of HMGB1 expression was found to be significantly closely associated with histopathology FIGO stage, and lymph node metastasis." (PMID 24837834, 2014). "Studies on other cancers also showed that HMGB1 expression was positively correlated with lymph node metastasis and distant metastasis." (PMID 22747650, 2012). "HMGB1 levels were significantly correlated with depth of invasion [Spearman correlation coefficients (γs) = 0.273 (p < 0.05)), and lymph node metastasis [Spearman correlation coefficients (γs) = 0.225 (p < 0.05)), but CEA levels were not." (PMID 19476625, 2009). "Moreover, high plasma HMGB1 concentrations were correlated with metastatic potential, such as venous invasion and lymph node metastasis, and worse RFS in GC patients." (PMID 35328684, 2022). "Adjuvant chemotherapy for patients with high HMGB1 expression, as well as patients with lymph-node metastasis, may be effective for some patients." (PMID 31399104, 2019).
lymph node metastasis (continued). "In contrast, HMGB1 expression grading was related with lymph node metastasis and FIGO stage." (PMID 24837834, 2014). "Furthermore, Cox univariate proportional hazards analysis showed that higher level of vascular invasion, parametrial infiltration, the depth of cervical stromal invasion, FIGO stage, lymph node metastasis, and HMGB1 expression predicted significantly shorter OS and DFS." (PMID 30962261, 2019). "In addition, HMGB1 levels were closely related with lymph node metastasis." (PMID 19476625, 2009). "Univariate regression analysis revealed that factors such as age, tumor location, histologic type, depth of invasion, lymph node metastasis, distant metastasis, AJCC stage, and HMGB1 expression significantly influenced survival (p < 0.05)." (PMID 40975711, 2025). "Univariate analysis revealed that tumor size, pT stage, lymph node metastasis, TNM stage, histological differentiation, HMGB1 expression, and VEGF-C expression were all significantly associated with poor survival rates (data not shown)." (PMID 23866030, 2013). "Furthermore, Cox’s multivariate analysis revealed that lymph node metastasis, TNM stage, HMGB1 expression, VEGF-C expression, and combined HMGB1/VEGF-C expression were significant predictors of survival." (PMID 23866030, 2013). "The expression of HMGB1 was significantly correlated with tumor size, pT stage, lymph node metastasis, and TNM stage but not with age, gender, pathological type, or tumor differentiation." (PMID 23866030, 2013). "We compared HMGB1 expression levels in two main histologic types (ADC and SCC) and metastasis (non-lymph node and lymph node metastasis)." (PMID 26840258, 2016).
steatosis (21 papers, 2014 to 2025). Increased lipid within the cytoplasm of cells. "In a murine LR model, inhibition of HMGB1 improved liver function, reduced steatosis, enhanced regeneration and decreased hepatic cell death." (PMID 39000266, 2024). "Since hepatic inflammation is one of the histological features distinguishing simple steatosis and NASH, HMGB1 likely mediates the transition from steatosis to NASH." (PMID 38002056, 2023). "Curcumin additionally reduced the steatosis and fibrosis of hepatocytes by modulating/inhibiting the high‐mobility group box 1 (HMGB1)‐NF‐κB translocation to prevent the NASH progression." (PMID 37457157, 2023). "HMGB1 plays a critical role in initiating and maintaining a chronic inflammatory state in the liver tissue, promoting the progression of steatosis to NASH." (PMID 36278177, 2022). "By contrast in mice fed EtOH+Chol, ALT increased to ~270 U/L, steatosis was more extensive and mostly macrovesicular, and expression of proinflammatory molecules (HMGB-1, TLR4, TNFα, ICAM-1) and leukocyte infiltration increased substantially." (PMID 27676640, 2016). "HMGB1 is rapidly released into the systemic circulation following liver reperfusion after LT, with HMGB1 levels correlating with the degree of graft steatosis and postoperative ALT levels." (PMID 24600525, 2014). "In steatosis hepatic, HMGB-1, releasing from hepatocytes in response to FFAs, is promoting an increased TLR4 protein levels and release of hepatic pro-inflammatory and pro-fibrogenic cytokines." (PMID 24829591, 2014). "Our murine LR model further demonstrated that inhibition of HMGB1 improved liver function, reduced steatosis, enhanced regeneration, and decreased hepatic cell death, highlighting the therapeutic potential of targeting HMGB1 in mitigating liver injury and promoting regeneration post LR." (PMID 39000266, 2024). "Intestinal flora-derived exosomes can mediate steatosis in hepatocytes carrying HMGB1." (PMID 36230535, 2022). "HMGB1 ablation in hepatocytes protects against steatosis and injury in ALD." (PMID 24928512, 2014). "Interestingly, we found that the baseline levels of platelet-derived and profibrotic TGF-ß1 (p=0.041), anti-apoptotic, angiogenic, proinflammatory high-mobility group box protein 1 (HMGB1) (p=0.047), and inflammatory pCXCR4 (p=0.003) were significantly elevated in patients with enhanced steatosis." (PMID 40860949, 2025). "Therefore, we next monitored whether the liver steatosis induced by hepatocyte Hmgb1 deletion has any effect on glucose homeostasis and/or insulin signaling in mice subjected to HFD60%." (PMID 35333579, 2022). "GLC could protect hepatocytes from oxidative stress and steatosis, and reduce extracellular HMGB1 levels, which blocks activation of macrophages via TLR4/NF-κB, and the expression of inflammatory cytokines was decreased to alleviate progression of steatohepatitis." (PMID 36278177, 2022). "HMGB1 exacerbates inflammation through activation of TLR4/MyD88 signaling and RAGE receptors in hepatocytes, resulting in pyroptosis, liver damage, steatosis, and impaired liver function." (PMID 39000266, 2024). "Strikingly, histological analysis showed that treatment with MCC950 reduced extranuclear translocation of HMGB1 and the number of ASK1+ hepatocytes and alleviated steatosis in ethanol‐fed old mice." (PMID 36999514, 2023). "Here, SalB confers protection against hepatic steatosis and inflammation through SIRT1-mediated HMGB1 deacetylation." (PMID 35873636, 2022). "Functional inhibition of HMGB1 by a neutralizing antibody in vivo also mitigated HFD-induced liver damage, steatosis, inflammation, and liver function impairment." (PMID 31731454, 2019).
steatosis (continued). "On the other hand, genetic deletion of HMGB1 in hepatocytes rapidly promoted HFD-induced weight gain and obesity, with enhanced hepatic fat deposition (steatosis)." (PMID 31731454, 2019). "Having demonstrated that steatosis in hepatocytes lacking HMGB1 is accompanied by ER stress, we wanted to examine this relationship further." (PMID 33238880, 2020). "Since liver inflammation is one of the histological markers that pathologically delineate simple steatosis from non-alcoholic steatohepatitis (NASH), HMGB1 could be a hepatic factor mediating the progression of steatosis to NASH." (PMID 31731454, 2019). "Undetectable levels of serum IL-33 and stable liver HMGB1 suggests the level of hepatocyte damage in our simple steatosis model is not severe enough to result in systemic release of these alarmins into the serum." (PMID 31034519, 2019). "HMGB1 kinetics did not correlate with either IL-6 or TNF-α, but with the degree of graft steatosis and postoperative ALT levels." (PMID 36338535, 2022).
endometriosis (20 papers, 2016 to 2026). The growth of functional endometrial tissue in anatomic sites outside the uterine body. "A recent study published showed that a research group developed a concept design of a testing device that detects HMGB1, which is another protein associated with endometriosis development." (PMID 41517625, 2026). "Recently, HMGB-1 has been implicated in endometriosis due to the important regulatory roles of inflammation in endometriosis." (PMID 33815277, 2021). "In the present study, we investigated the roles of HMGB-1 in endometriosis and its underlying mechanisms." (PMID 33815277, 2021). "The aim of the present study was to explore the roles of HMGB-1 in endometriosis and to elucidate the underlying mechanism." (PMID 33815277, 2021). "To confirm that the role of HMGB-1 in endometriosis was associated with inflammatory cytokines, we analyzed the correlations between HMGB-1 and inflammatory cytokines in HESCs." (PMID 33815277, 2021). "Therefore, in the present study, we aimed to explore the roles of HMGB-1 in endometriosis and its underlying mechanisms." (PMID 33815277, 2021). "Because of the observed increase in expression in the early and mid-secretory phases, aberrant expression of HMGB-1 may be associated with interrupted implantation in patients with endometriosis, which may partly explain the development of progesterone resistance in women with endometriosis." (PMID 26872033, 2016). "High Mobility Group Box 1 (HMGB1) and S100 proteins are major ligands of Receptor for Advanced Glycation End-products (RAGE) and have causal roles in endometriosis lesions." (PMID 41683818, 2026). "This approach enabled the construction of a functional lateralflow assay to detect HMGB-1, a key biomarker for endometriosis inmenstrual effluent at low concentrations." (PMID 40893952, 2025). "To assess the efficiency of these techniques,along with their sensitivity, limit of detection (LOD), and dynamicclinical detection range, we targeted HMGB-1, a biomarker for endometriosis, using menstrual blood to advancewomen’s health diagnostics." (PMID 40893952, 2025). "During this period, high mobility group box 1 (HMGB-1) levels (cellular damage marker) sharply increase in endometrium of women with endometriosis." (PMID 41488658, 2025). "It appears that NF-kB inhibitors and TLR4 agonists lead to the suppression of HMGB1 and decreases in IL-6 levels, demonstrating their involvement in endometriosis and the clinical relevance of this new finding." (PMID 38337827, 2024). "One study assessed the diagnostic performance of high mobility group box-1 (HMGB1) and toll-like receptor 4 (TLR4), which seem to be associated with this process of damage-associated molecular patterns (DAMPs) and induce endometriosis." (PMID 38337827, 2024). "In endometriosis, prostaglandin E2 increased the expression of HMGB1 and promoted the process of pyroptosis." (PMID 37945340, 2023). "In addition, the effects of HMGB1 on endometriosis may be linked to pyroptosis." (PMID 37691930, 2023). "There are other components of innate immunity, including TNF-α, IL-1β, IL-6, IL-17A, ICAM-1/LFA-1, and HMGB-1, that participate in the pathogenesis of endometriosis." (PMID 36865552, 2023). "Apart from COX-2, the high mobility group box (HMGB)-1 is another inflammatory mediator reported to be involved in the development of Endometriosis." (PMID 34964708, 2022). "HMGB-1- mediated inflammation and autophagy are reportedly critical inducers for the development of Endometriosis." (PMID 34964708, 2022). "Meanwhile, to confirm the regulatory role of HMGB-1 in endometriosis, we silenced HMGB-1 in HESCs under hypoxic conditions." (PMID 33815277, 2021). "Our study demonstrated that endometriosis induced the expression of HMGB1 in the transplant, dorsal root ganglion, and spinal dorsal horn." (PMID 33673857, 2021). "To explore the roles of HMGB-1 in endometriosis, we knocked down HMGB-1 in the HESCs by using a lentiviral vector carrying HMGB-1 shRNA." (PMID 33815277, 2021).